AKAIN1 (A-kinase anchor inhibitor 1)
Description:
Protein kinase A (PKA)-binding protein. Binds to type II regulatory subunits of protein kinase A (PKA) and may block the A-kinase anchoring protein (AKAP)-mediated subcellular localization of PKA.
Synonyms: C18orf42
Tractability: No criterion of Open Targets' tractability assessment is met for any kind of drug.
Gene: Protein-coding gene on chromosome 18 (5,142,911 to 5,197,503, reverse strand). Ensembl gene ENSG00000231824.
Gene Ontology:
Molecular function: protein binding; protein kinase A binding
Biological process: intracellular protein localization
Cellular component: cytosol
Genetic constraint (gnomAD): Loss-of-function variants: 3 observed, 4.96 expected, observed/expected ratio (o/e) 0.6, 90% interval 0.27 to 1.51. That is too few expected variants to judge how well the gene tolerates losing a copy. Missense variants: 82 observed, 86.89 expected, observed/expected ratio (o/e) 0.94, 90% interval 0.79 to 1.13. Synonymous variants: 31 observed, 32.86 expected, observed/expected ratio (o/e) 0.94, 90% interval 0.71 to 1.27.
Homologues: Orthologues: chimpanzee AKAIN1 (93% identical), macaque AKAIN1 (91% identical), dog AKAIN1 (88% identical), rabbit AKAIN1 (87% identical), rat Akain1 (80% identical), mouse Akain1 (77% identical), pig AKAIN1 (77% identical), tropical clawed frog akap7 (25% identical). Paralogues in human: AKAP7 (22% identical).